RN7SL618P (RNA, 7SL, cytoplasmic 618, pseudogene)
Gene: Miscellaneous RNA gene on chromosome 13 (53,258,077 to 53,258,372, forward strand). Ensembl gene ENSG00000241613.
Homologues: Orthologues: chimpanzee Metazoa_SRP (98% identical), macaque Metazoa_SRP (93% identical). Paralogues in human: RN7SL1 (84% identical), RN7SL2 (83% identical), RN7SL3 (83% identical), RN7SL566P (82% identical), RN7SL597P (82% identical), RN7SL220P (82% identical), RN7SL448P (80% identical), RN7SL664P (80% identical), RN7SL868P (80% identical), RN7SL278P (80% identical), RN7SL296P (80% identical), RN7SL416P (80% identical), and 701 more.
Diseases named in the same sentence as RN7SL618P in open-access papers:
RN7SL618P is named in the same sentence as 1 disease in open-access papers, as found by Europe PMC text mining. Sharing a sentence is not in itself a finding about the gene and the disease. The quoted sentences say what the papers report.
cancer (1 paper, 2022). A tumor composed of atypical neoplastic, often pleomorphic cells that invade other tissues. "The strongest association signal for PTSD was found on chromosome 13 (P = 4.79 × 10–20), in a region spanning noncoding mRNAs LINC01065, PCDH8P1, and RN7SL618P as well as olfactomedin 4–encoding gene OLFM4, which takes part in innate immunity, inflammation, and cancer." (PMID 33905376, 2022).